TNF (tumor necrosis factor)
Diseases named in the same sentence as TNF in open-access papers (continued):
Sharing a sentence is not in itself a finding about the gene and the disease.
Sepsis (continued). "TAK-242 was developed as a small-molecule selective inhibitor of TLR4 signaling that suppresses the increase in serum cytokine levels TNF-a, IL-1, and IL-6 in murine and porcine models of sepsis, as well as in LPS challenged healthy volunteers." (PMID 30405628, 2018). "TNF-α concentration was increased by more than double in sepsis-induced group compared with the sham group; in UTI pretreatment group, it was suppressed by about 40%." (PMID 30150933, 2018). "EA at Zusanli had a positive role in myocardial injury of sepsis rats by reducing the high TNF-α, MPO, and NO content, lowering plasma activity of CK-MB and moisture content." (PMID 30402132, 2018). "Significant reductions in the levels of circulating interleukin-6 (P = 0.046) and tumor necrosis factor-α (P = 0.008) were found in the sepsis group." (PMID 30666251, 2018). "This ameliorated septic response in oxPAPC/LPS-injected mice was further emphasized by the significant reduction of serum tumor necrosis factor (TNF) levels, which is a key marker of sepsis." (PMID 29520027, 2018). "Treatment with LPS, an important pathogenicity factor that lead to cardiac depression in experimental sepsis, significantly stimulated TNF-α and VCAM-1 expression in rat CMECs." (PMID 29615637, 2018). "Our findings of elevated TNFα and IL-6 levels in sepsis-induced AKI are consistent with these reports." (PMID 30343340, 2018). "Murine CLP models have demonstrated enhanced TNFα production in splenic inflammatory monocytes and brain microglia for at least 2 weeks after sepsis suggesting a possible link between primed cells and long-term organ dysfunction." (PMID 30459764, 2018). "We next employed pharmacologic blockade of the α7nAChR to confirm that suppression of LPS-triggered TNFα responses in sepsis surviving mice occurs through the cholinergic pathway." (PMID 30237803, 2018). "Lipopolysaccharide (LPS) and sepsis-related inflammatory factors such as TNF-α and IL-6 can regulate the secretion of PCT." (PMID 30595763, 2018). "Based on our findings, HBP plays an important role in the initial inflammatory reaction associated with sepsis-induced AKI, presumably by activating M1 macrophages and suppressing TNF-α and IL-6 secretion." (PMID 29723248, 2018). "The characteristic of the first phase of sepsis is the production of proinflammatory cytokines, including tumor necrosis factor-alpha (TNF-α), interleukin- (IL-) 1β, IL-6, and IL-8." (PMID 29636842, 2018). "The mechanisms responsible for these effects, at least in part, involve the inhibition of TNF-α expression via suppressing NF-κB and MAPKs pathways during sepsis." (PMID 30150933, 2018). "The TNF-α, IL-1β, and IL-6 concentrations in patients with sepsis were markedly greater compared to those in the controls, and the levels also increased with the development of sepsis." (PMID 30268141, 2018). "Therapies with anti-Toll-like receptor 4, anti-TNF-α, and activated protein C failed in clinical trials, requiring a rethinking of sepsis pathophysiology." (PMID 30538802, 2018). "Monocytes and neutrophils produce IL-1β, tumor necrosis factor-α (TNF-α), and IL-10, cytokines constituting the storm during sepsis." (PMID 30538802, 2018). "To investigate the epigenetic changes occurring at the HIV-1 promoter during the LRA challenges, we treated all J-Lat 9.2 cell lines for 48 h with 5 ng/mL of TNF; equivalent to the highest pathological TNF concentration reported in human serum during sepsis." (PMID 30286764, 2018). "A similar pattern of decreased TNFα, IL-6, IFNγ, and IL-10 was also observed in a post-mortem study of stimulated splenocytes from patients who died of sepsis." (PMID 30555806, 2018). "Cytokine changes have been extensively studied in patients with septicemia or after exposure to endotoxin with sequential increases in TNF-α, IL-1β, IL-6, IL-1Ra, and IL-10." (PMID 29149303, 2018).
Sepsis (continued). "Circulating levels of the cytokines IL-6, IL-8, IL-10, MCP-1, IP-10, and TNF were significantly increased in septic patient at all three time points (<12 hours, 4 days, and 14 days after sepsis) compared to healthy controls." (PMID 30300408, 2018). "It has been established that myocardial TNF-α and apoptosis contribute to sepsis-induced cardiomyopathy, NF-κB and p38 activation mediate LPS-induced TNF-α expression, and JNK phosphorylation involves sepsis-induced apoptosis in cardiomyocytes." (PMID 29615637, 2018). "Type II cytokines play a crucial role in sepsis which include the tumor necrosis factor (TNF) family, the interferon (IFN) family, and the immunoglobulin family." (PMID 29780830, 2018). "As one of the inflammatory mediators involved in sepsis, TNF-α is an important inflammatory cytokine during the early stage of inflammation and is mainly produced by monocytes and macrophages." (PMID 30249753, 2018). "We suggest that the real importance of TNF-α, which is thought to play an important role in the pathogenesis of sepsis, and the periods in which TNF-α plays an active role during the disease should be determined in large population studies." (PMID 28840846, 2018). "On the other hand, males present predominantly Th1 responses and overproduce tumor necrosis factor α (TNF-Uα), IL-1β, IL-2, IL-6, and IL-8, which in turn are frequently associated with inappropriate outcomes such as sepsis and bacteremia." (PMID 29925409, 2018). "TNF-α and IL-1β were measured to assess the presence of neuroinflammation in the cortex and hippocampus of the sepsis survivors." (PMID 30186119, 2018). "For example, it reduces serum TNF-α and IL-6 concentrations in patients and in preclinical models of sepsis, antagonizes LPS, regulates CD4+ T cell differentiation, and prevents/controls the disseminated intravascular coagulation (DIC) and infections." (PMID 30618740, 2018). "Bolus injection of endotoxin induces initial characteristics of human sepsis such as activation of innate immune system and rises in TNFα." (PMID 29445877, 2018). "High levels of TNF-α and IL-1β in sepsis are generally considered to be correlated with high mortality, while IL-12, the primary effector of monocytes, can synergize IFN-γ to promote the inflammatory response, leading to poor prognosis of sepsis." (PMID 29662678, 2018). "Hendriks demonstrated that peritoneal cytokine levels (especially IL-6, TNF-α, and IL-10) were dramatically different in rats who either survived or succumbed to an intra-peritoneal sepsis model in the 24 h after cytokine determination." (PMID 29977328, 2018). "TNFα and IL-6 are recognized early players in the clinical response to sepsis and shown to be locally produced by intrinsic kidney cells in the early phase of injury." (PMID 30343340, 2018). "In this study we analyzed the impact of PLD1 in the regulation of TNF-α, inflammation and organ damage in experimental sepsis." (PMID 29968773, 2018). "Our data show association between serum levels of the cytokines IL-4, IL-6, IL-10 and TNF, and cognitive performance of patients with severe sepsis or septic shock." (PMID 29540719, 2018). "The reduction in LPS-induced TNFα observed in sepsis surviving mice can be partially restored by vagotomy, which severs the vagus nerve." (PMID 30237803, 2018). "Only the levels of IL-6 and TNF-α were decreased in the AKI with sepsis group (P = 0.046 and P = 0.008, respectively)." (PMID 30666251, 2018). "Similar results were obtained for the levels of the proinflammatory cytokines, TNF-α and IL-1β, indicating that SIRT3 knockout increased inflammatory responses associated with sepsis-induced AKI through the AMPK/mTOR/autophagy pathway." (PMID 30487750, 2018). "Diabetes exacerbates serum tumor necrosis factor (TNF) levels in sepsis by increasing splenic TNF production." (PMID 29780390, 2018).
Sepsis (continued). "It has been widely studied in rodent sepsis models and has been identified as a late mediator of lethal systemic inflammation released by macrophages after stimulation with endotoxin, TNF, or IL-1." (PMID 29791477, 2018). "The peak levels of TNF-α (i.e., a primary mediator of septic shock and organ failure) were considerably higher than the levels commonly observed in patients with sepsis." (PMID 29850597, 2018). "At the molecular level, a link between “cytokine storm” and sepsis has been established, which is defined as the abnormal increase in the levels of different cytokines, including tumor necrosis factor (TNF) and interleukin-1 (IL-1)." (PMID 30086151, 2018). "In mammals including humans, there is a so called “cholestasis of sepsis”, in which systemic pro-inflammatory cytokines like IL-1β and TNF-α lead to downregulation of bile acid transporter proteins and to canalicular and ductular cholestasis." (PMID 30149505, 2018). "HBP plays an important role in the initial inflammatory reaction associated with sepsis-induced AKI, presumably by activating M1 macrophages and suppressing TNF-α and IL-6 secretion." (PMID 29723248, 2018). "Increased levels of TNF-α have been found in sepsis, but TNF-α inhibition has proven to be an unsuccessful treatment." (PMID 28840846, 2018). "CLP-sepsis in mice on HFD resulted in large increases in the serum levels of TNF-α, IL-6, KC, and IL-10 when compared to mice on HFD subjected to sham surgery and mice on chow diet subjected to CLP (P < 0.05)." (PMID 30619349, 2018). "Thereby, it was an earlier indicator for inflammation than the increase of the pro-inflammatory cytokines IL-6 and TNF-α, which reached statistical significance two hours after induction of sepsis." (PMID 30060473, 2018). "The effects of TNF can diverge at the level of TNF format or receptor, and we discuss the consequences of this in sepsis, autoimmunity and neurodegeneration." (PMID 29751683, 2018). "Our finding that blockade of the TLR4–NF-κB pathway or TNF-α can reverse impaired myogenesis suggests a new set of drug targets for clinical intervention in sepsis- or metabolic endotoxemia-induced muscle debilitation." (PMID 28742154, 2017). "In an LPS-induced shock mouse, which is considered to be a model of sepsis, serum cytokines such as IL-6 and TNF-α were increased, and these cytokines induced organ injury and mortality." (PMID 28800777, 2017). "Clinical sepsis scores were monitored; serum cytokines (TNF-α, IL-6, IL-10) and chemokines (MIP-1α) were measured at the end." (PMID 28759625, 2017). "In both LPS-induced and CLP-induced sepsis models, TNF-α level, as well as other cytokines, was significantly increased in platelet CLEC-2-deficient animals compared to their littermate controls." (PMID 29269852, 2017). "The splenectomy abolished TNF reduction resulting from stimulation of vagal nerve efferents in sepsis." (PMID 28197102, 2017). "We measured TNFα after incubation of whole blood with Salmonella enterica-derived LPS and observed reduced TNFα response in sepsis patients and after surgical trauma compared to controls." (PMID 28771573, 2017). "The concentrations of IL-1β, IL-6, and TNF-α were significantly higher in the sepsis groups than those in the NC group." (PMID 28513569, 2017). "Among the inflammatory cytokines, TNF-α is believed to be a primary mediator of sepsis, since direct infusion of animals with recombinant TNF-α produces most of the adverse events observed after LPS administration." (PMID 28915246, 2017). "Before, and at 12, 18 and 22 h of progressive sepsis, systemic and renal hemodynamics, cortex microcirculation and plasma IL-6 and TNF-α were measured." (PMID 28569136, 2017). "We found that plasma concentrations of TNF-α, IL-1β and IL-6 in the sepsis group were significantly higher than in the healthy control group, and the levels of these cytokines also increased with sepsis severity." (PMID 28472164, 2017).
Sepsis (continued). "This is presumably what prevents specific anti-TNF neutralizing agents from being clinically useful in patients who are acutely ill from sepsis." (PMID 28451786, 2017). "The activation of NF-κB (p65) was proved to play important roles in the development and progression of sepsis through enhancing the transcription of various pro-inflammatory cytokines including TNF-α, IL-1β, IL-6." (PMID 28430592, 2017). "White blood cells (WBCs), neutrophils, monocytes, and macrophages have been reported to be highly recruited and activated following the release of inflammatory mediators such as TNF-α and ·NO in the animal system during the progression of sepsis." (PMID 28067837, 2017). "Pro-inflammatory cytokines including tumor necrosis factor α (TNFα), IL-1β, IL-6, and IL-8 are potent immune mediators that exacerbate multiple equine diseases such as sepsis and laminitis." (PMID 29034249, 2017). "While plasma IL-6, TNF-α, and IL-1β levels are also reported as predictors of death from sepsis, in our study the utility of IL-8 was much greater." (PMID 28167592, 2017). "At onset of infection, SIRS-N patients had the lowest median IL10/TNF ratio (1.2) with progressively increasing value as severity of sepsis increased, at 1.5, 3.0, and 4.5 for patients with sepsis, severe sepsis, and septic shock, respectively." (PMID 31058274, 2017). "CORM administration was able to inhibit sepsis-induced NF-κB activation in lung and liver and reduced serum cytokine levels of IL-6 and TNF-α." (PMID 28655348, 2017). "TNFα response to LPS was decreased in all patients (median 319 pg/mL versus controls 1256 pg/mL; P<0.01) and lowest in patients with sepsis or septic shock (median 128 pg/mL; P<0.01)." (PMID 28771573, 2017). "Several cytokines are produced in pro-inflammatory state during sepsis, such as the representative and most familiar, tumor necrosis factor-α (TNF-α)." (PMID 29207683, 2017). "The plasma concentrations of TNF-α, IL-6 and IL-1β were significantly higher in the sepsis patients compared to the healthy volunteers (P < 0.0001), and that they increased with the aggravation of sepsis (P < 0.05)." (PMID 28839236, 2017). "Excessive release of inflammatory factors, such as IL-1β, IL-6, and TNF-α, triggered pathophysiological abnormities of sepsis." (PMID 28994737, 2017). "The level of TNF‐α was increased from 10.8 ± 0.9 in the sham group to 20.4 ± 5.2 pg/mL in the sepsis group (P < 0.05), confirming the development of an inflammatory reaction in the sepsis group." (PMID 28684640, 2017). "Following massive microbial infection, highly produced inflammatory cytokines, mainly TNF-α and IL-1β, drive hyperinflammation in sepsis patients." (PMID 28533774, 2017). "During the early phase of sepsis, human monocytes are triggered to produce copious quantities of inflammatory cytokines such as TNFα in response to bacterial pathogens." (PMID 28771573, 2017). "Among the three sepsis subgroups, the plasma concentrations of TNF-α, IL-6 and IL-1β in the severe sepsis/septic shock subgroups were significantly higher compared with the mild sepsis subgroup." (PMID 28472164, 2017). "A sepsis-like inflammatory response to LPS was confirmed by the expression of classical cytokines such as TNFα and IL-6." (PMID 28276491, 2017). "In the present study, TNFα, IL-1β and IL-6 transcript levels were all increased in gastrocnemius and diaphragm muscles during sepsis, but this response was significantly greater and more sustained over time in the diaphragm muscle." (PMID 28883493, 2017). "The NF-κB pathway is one of the main mechanisms for secreting large numbers of pro-inflammatory cytokines, such as TNF α, worsening the systemic inflammatory response in sepsis." (PMID 29100348, 2017). "We found that sepsis Arrb2 TG mice were immunosuppressive, characterized by reduced pro-inflammatory (TNF-α, INF-γ) and increased anti-inflammatory (IL-10, IL-4) cytokines expression." (PMID 28525390, 2017).
Sepsis (continued). "In conclusion, 5-HT increased serum cytokine secretion, such as TNF-α and IL-6, and aggravated the mortality of sepsis by an excessive inflammatory response." (PMID 28694565, 2017). "Pro-inflammatory cytokines such as TNF-α, IL-1ß, and IL-6 play a more important role in the pathogenesis of sepsis and septic shock." (PMID 28320333, 2017). "Their results demonstrated a defective response of monocytes and lower TNF-α levels in both patients with sepsis and patients with cardiogenic shock compared with healthy control subjects." (PMID 28274246, 2017). "CGA-JK3 consequently interrupted IKKβ-inducible NF-κB activation and NF-κB-regulated expression of TNF-α, IL-1α or HMGB-1 gene, thereby improving TLRs-associated redundant inflammatory responses in endotoxemia, polymicrobial sepsis and ALF." (PMID 28145460, 2017). "During the early hyperinflammatory phase of sepsis, plasma levels of proinflammatory cytokines TNF-α and IL-6, as well as the chemokine monocyte chemoattractant protein 1 (MCP-1/CCL2), are dramatically increased." (PMID 28628637, 2017). "Future studies should consider comparing the effective concentrations of systemic and local cytokines, in an attempt to reconcile the literature about the importance and detriment of TNF-α in early sepsis." (PMID 28105603, 2017). "In animals with sepsis, Fpr2/3 gene activation can be induced by TNF-α, and FPR2/ALX activation can decrease TNF-α levels." (PMID 28679406, 2017). "Key mediators of pathologic sequelae of sepsis in the brain include cytokines, including TNF-α, and sphingolipids, which are biologically active components of cellular membranes that possess diverse functions." (PMID 28670310, 2017). "CV failure on admission is a major indicator of the likelihood for defective TNF-α responses over the time course of sepsis." (PMID 28274246, 2017). "In more detail, Granzyme A and M are involved in the production of IL-1α, IL-1β, TNF, and IFNγ after bacterial stimuli, and also in the development of sepsis." (PMID 28850071, 2017). "As reviewed, hypoalbuminemia is also a characteristic of malaria, sepsis, acute viral diseases, and severe trauma, all conditions with high TNF." (PMID 28451786, 2017). "In animal models of sepsis, pretreatment with G-CSF attenuated serum levels of TNF induced by LPS, as well as ex vivo TNF release in different populations of macrophages." (PMID 28769538, 2017). "The IL-10/TNF-α ratio, which is a marker of the balance between anti-inflammatory and hyper-inflammatory states in sepsis, was assessed." (PMID 28918754, 2017). "Because phagocytic cells are the major source of inflammatory mediators, such as tumor necrosis factor-α (TNF-α), interleukin (IL)-1β, IL-6 and matrix metalloproteinases (MMPs), involved in the pathogenesis of sepsis." (PMID 28661460, 2017). "During sepsis, the burst of inflammatory mediators (e.g., TNF-α) increases membrane rigidity of neutrophils, which limits tissue migration of neutrophils." (PMID 28442605, 2017). "Serum and plasma TNF-α levels have been shown to increase significantly among patients with sepsis, particularly in culture-positive patients." (PMID 28692671, 2017). "This meta-analysis of 23 eligible articles comprehensively and quantitatively evaluated the effects of tumor necrosis factor-α (TNF-α) rs1800629 and rs361525 polymorphisms on sepsis risk." (PMID 29340067, 2017). "Vogl and colleagues showed that S100A8/A9 amplifies phagocyte activation during lipopolysaccharide-induced sepsis via activation of TLR-4 upstream of TNF-α response." (PMID 28672877, 2017). "Elevated TNF-α levels enhance the inflammatory response and lead to the multiple phenotypic and functional characteristics of sepsis; they also induce apoptosis and reduce immune responsiveness and cell function." (PMID 29212277, 2017).